MYCN (MYCN proto-oncogene, bHLH transcription factor)
Diseases named in the same sentence as MYCN in open-access papers (continued):
Sharing a sentence is not in itself a finding about the gene and the disease.
microcephaly (9 papers, 2010 to 2026). A congenital or acquired developmental disorder in which the circumference of the head is smaller than normal for the person's age and sex. "In addition to tumorigenesis, MYCN is also crucial for embryonic development, as it is expressed in human fetal brain, and heterozygous MYCN mutation causes microcephaly and learning disability in human." (PMID 34625907, 2022). "The second-trimester ultrasound revealed bilateral clinodactyly and fetal microcephaly, and the subsequent molecular karyotyping identified a ~342 kb deletion at 2p24.3 encompassing the MYCN gene, confirming the diagnosis." (PMID 41595474, 2026). "Among them, two members, MYCN and TCF4, will be highlighted here for their association with microcephaly." (PMID 38094004, 2023). "MYCN loss-of-function variants are known to be implicated in the Feingold disorder (microcephaly and absent/hypoplastic phalanx), with a mirror phenotype of the fetus (macrocephaly and polydactyly)." (PMID 37035737, 2023).
multiple myeloma (8 papers, 2014 to 2025). "Among the genes uniquely expressed following Ix-treatment in resistant myeloma were RICTOR (activated), HNF4A, miR-16-5p (activated), MYCN (inhibited), and MYC (inhibited)." (PMID 32724061, 2020).
prostate adenocarcinoma (8 papers, 2017 to 2024). "Amplification and overexpression of MYCN and AURKA genes have been observed in confirmed t-NEPC tissue, and both induce a neuroendocrine cell phenotype in prostatic adenocarcinoma cells through transcriptional reprogramming mechanisms." (PMID 34386489, 2021). "Using tissue sourced from benign prostate, prostate adenocarcinoma, and NEPC, a significant overexpression and gene amplification of the protooncogenes MYCN and its stabilising cofactor Aurora kinase A (AURKA) were discovered in 40% of NEPC and 5% of prostate adenocarcinomas." (PMID 39682746, 2024).
adrenal tumors (7 papers, 2013 to 2023). "In this scenario, the high frequency of the SCAs and MYCN amplifications in adrenal tumors would be caused by different sensitivities of chromaffin cells and neuroblasts to oncogenic signals." (PMID 35681734, 2022). "These patients had the typical characteristics of high-risk NB: 85% (17/20) were ≧18 months old, 95% (19/20) with INRG stage M, 50% (10/20) with MYCN-amplified tumor, 95% (19/20) with BM metastasis at diagnosis, 80% (16/20) with adrenal gland tumor." (PMID 36276741, 2022). "Adrenal tumors more often display segmental chromosomal aberrations (SCAs), including MYCN amplifications, compared to ganglionic tumors, which exhibit rather numerical chromosomal aberrations." (PMID 35681734, 2022). "The enrolled patients showed the typical characteristics of HR-NB: a median of 42 months old at diagnosis (range 30–75 months), 86% (6/7) with an adrenal gland tumor, 29% (2/7) with a MYCN-amplified tumor, 71% (5/7) with BM metastasis at diagnosis, and 86% (6/7) with INSS stage 4." (PMID 37887060, 2023).
colon carcinoma (7 papers, 2014 to 2023). "Furthermore, we have identified significant upregulation of key transcription factor interactions in colon cancer patients, including the apoptotic regulation facilitated by E2F1, MYC, and MYCN, as well as activation of the BCL-2 protein family facilitated by TP73." (PMID 37398471, 2023).
diffuse intrinsic pontine glioma (7 papers, 2016 to 2026). A neuroglial tumor that arises from the middle portion of the brain stem. "MYCN-dependent transcription can also be affected, as demonstrated in NB cells, or contribute to histone-3 methylation in diffuse intrinsic pontine glioma (DIPG)." (PMID 36839989, 2023). "The high level of MYCN in diffuse intrinsic pontine glioma (DIPG) led investigators to test sequential therapy with the bromodomain inhibitor JQ1, which targets MYCN, and the gamma-secretase inhibitor MRK003, which targets NOTCH." (PMID 27382528, 2016).
non-small cell lung carcinoma (7 papers, 2016 to 2026). A group of at least three distinct histological types of lung cancer, including non-small cell squamous cell carcinoma, adenocarcinoma, and large cell carcinoma. "Among them, Nobiletin was reported to enhance chemosensitivity to adriamycin by modulating the Akt/GSK3β/β-Catenin/MYCN/MRP1 signalling pathway in A549 human non-small cell lung cancer cells." (PMID 41579221, 2026). "Additionally, MYCN has been shown to contribute to chemoresistance in non-small cell lung cancer (NSCLC) by binding to the HES1 promoter, which suppresses apoptotic pathways." (PMID 40593489, 2025).
bladder cancer (6 papers, 2015 to 2025). "In summary, this study elucidates the oncogenic role of PKIB and uncovers a novel MYCN-PKIB-PKA-HSP27 signaling axis in bladder cancer (BLCA), advancing our understanding of PKA-mediated regulatory mechanisms in tumorigenesis." (PMID 40593489, 2025). "In addition, circLAMA3 targets MYCN mRNA and promotes its degradation, reducing MYCN expression in bladder cancer cells." (PMID 38915053, 2024). "In conclusion, our data suggest that high expression of PKIB, regulated by MYCN, mediates reduced HSP27 phosphorylation through inhibition of PKA kinase activity, thereby inducing a malignant phenotype in human bladder cancer." (PMID 40593489, 2025).
bone metastasis (6 papers, 2021 to 2026). Transfer of a neoplasm from its primary site to bones. "Results from multivariate Cox analysis identified INSS stage, bone metastasis, MYCN, and LAR as independent prognostic factors for OS." (PMID 41749576, 2026).
lung adenocarcinoma (6 papers, 2014 to 2022). A carcinoma that arises from the lung and is characterized by the presence of malignant glandular epithelial cells. "Previous work has established MCM10 is regulated by MYCN, an oncogene known to be mutated in several subtypes of lung adenocarcinoma (Rickman, Schulte & Eilers, 2018)." (PMID 33604163, 2021). "Therefore, we hypothesize aberrant MYCN function may directly result in amplification of MCM10, which then potentiates lung adenocarcinoma pathogenesis." (PMID 33604163, 2021).
B-cell lymphoma (5 papers, 2016 to 2024). "I would be expected that MYCN overexpressing tumors would have elevated rates of ribosome biogenesis, and their malignancy dependent on this process as has been described in c-Myc-driven tumors model of B-cell lymphoma." (PMID 26728659, 2016).
breast tumors (5 papers, 2012 to 2025). "Three of the four genes were overexpressed in breast tumors arising in younger women compared to older women: BUB1 (Fold Change 1.67, p = 0.029), KRT5 (Fold Change 1.56, p = 0.002), and MYCN (Fold Change = 1.16, p = 0.027)." (PMID 25999348, 2015).
gastric cancer (5 papers, 2012 to 2024). A primary or metastatic malignant neoplasm involving the stomach. "Moreover, the targeted inhibition of LINC01106 has shown potential in curbing the aggressive traits of gastric cancer cells by interacting with the miR-34a-5p/MYCN pathway." (PMID 38255219, 2024).
neural tumors (5 papers, 2009 to 2024). "Nevertheless, primary tumors of MYCN transgenic mice did not give rise to tumorspheres in a serum-free neurosphere culture condition, which is commonly used for tumorsphere cultures for neural tumors." (PMID 24466252, 2014).
neuroblastic tumor (5 papers, 2013 to 2024). A group of nervous system tumors which display neuronal differentiation. "TH-MYCN mice express the human MYCN gene under the control of the rat tyrosine hydroxylase (Th) promotor, which results in neuroblastic tumors in about 50% of transgenic animals." (PMID 29492199, 2018). "In the study, we evaluated the histological presentation and MYCN gene copy number in 220 pediatric neuroblastic tumors, which include 178 NBLs, 32 GNBLs and 10 GNs and analyzed their association with clinical outcome of the patients." (PMID 23320395, 2013). "MYCN gain is a recurrent genetic aberration of neuroblastic tumors (71.8%, 158/220), which was found in 129 NBLs (58.6%, 129/220), 25 GNBLs (11.4%, 25/220) and 4 GN cases (1.8%, 4/220)." (PMID 23320395, 2013). "A deep learning model using attention-based multiple instance learning (aMIL) and self-supervised learning (SSL) was developed to perform pathologic classification of neuroblastic tumors and assess MYCN-amplification status using H&E-stained whole slide digital images." (PMID 38883758, 2024). "It was found significantly overexpressed in MYCN nonamplified neuroblastic tumors, in patients with age at diagnosis < 18 months, and in those with lower clinical stages." (PMID 31293052, 2019). "On the other hand, PTHLH is highly expressed in well‐differentiated, Schwannian stroma‐rich neuroblastic tumors and high levels of PTH1R expression are associated with MYCN nonamplified, benign neuroblastomas." (PMID 31293052, 2019).
neuroendocrine carcinoma (5 papers, 2020 to 2025). A malignant neuroendocrine neoplasm composed of cells containing secretory granules that stain positive for NSE and chromogranin. "MYCN is also associated with tumors arising from the neural system and is commonly expressed in all forms of neuroendocrine cancers." (PMID 35883689, 2022). "This study provides insights into an oncogenic positive feedback circuit in MYCN-driven neural and neuroendocrine cancers." (PMID 33425720, 2020). "Here, we investigated whether MDM2 upregulates MYC as well as MYCN in selected neural and neuroendocrine cancers." (PMID 33425720, 2020). "Identifying these roles in human cancer-originating cells may provide opportunities to interfere with the genesis and propagation of MYCN-driven neural and neuroendocrine cancers." (PMID 33425720, 2020).
pediatric tumors (5 papers, 2018 to 2025). "Epigenetic changes are considered to be a fundamental hallmark of pediatric tumors including neuroblastoma, and previous studies have shown that MYCN is able to interact with and recruit PRC2 to epigenetically suppress target genes, a process that appears to be essential for MYCN oncogenesis." (PMID 38992040, 2024).
primitive neuroectodermal tumor (5 papers, 2012 to 2023). A malignant neoplasm that originates in the neuroectoderm. "Remarkably, we found that, among different tumors, CNTFR showed the highest expression in SCLC and NB, which are two MYCN-related neuroectodermal tumors." (PMID 36765949, 2023). "Interestingly, MYCN showed high-level focal amplifications in a subset of GBM samples, and MYC or MYCN is found to be amplified in almost half of brain cancers that have combined features of malignant glioma and primitive neuroectodermal tumors (MG-PNET)." (PMID 22348395, 2012).
sarcoma (5 papers, 2017 to 2023). A usually aggressive malignant neoplasm of the soft tissue or bone. "In comparison, MYC was upregulated in F9 MB-WNT that showed both MYCN and MYC high overexpression, and also in M6 high-grade sarcoma." (PMID 35978432, 2022).
subependymoma (5 papers, 2023 to 2025). Subependymoma is a rare and slow growing type of ependymoma, often presenting in middle-aged adults, found more commonly in men than in women, usually located in the fourth and lateral ventricles and manifesting with variable symptoms including headache, nausea, and loss of balance. "By definition, it lacks histopathological features of myxopapillary ependymoma or subependymoma and MYCN amplification." (PMID 38074692, 2023). "The WHO 2021 classification of spinal cord ependymomas includes spinal ependymoma (SP-EPN), spinal ependymoma with N-Myc (also known as MYCN) amplification (SP-MYCN), myxopapillary ependymoma (MPE), subependymoma (SE), and neurofibromatosis 2 (NF2)-mutated variants (with losses on chromosome 22q)." (PMID 41154124, 2025). "Therefore, the fifth edition of the WHO classification of CNS tumors categorizes spinal ependymal tumors into four different subtypes: spinal ependymoma, spinal ependymoma MYCN-amplified, myxopapillary ependymoma, and subependymoma." (PMID 38074692, 2023). "Spinal cord ependymal tumors comprise four distinct tumor types: spinal ependymoma (SP-EPN), spinal ependymoma with MYCN amplification (SP-MYCN), myxopapillary ependymoma (MPE), and subependymoma (SE)." (PMID 41050069, 2025).
adrenal neuroblastoma (4 papers, 2015 to 2023). "As adrenal neuroblastoma shows a much higher incidence of MYCN amplification and segmental genomic aberrations, it should be noted that the BET pathways include effects on genomic stability." (PMID 35681734, 2022). "Our patient is a 6 years-old girl with relapsed adrenal neuroblastoma, INSS-stage 4, unfavorable histology and without information in regard to amplification of MYCN gene (MYCN-amplification)." (PMID 26337867, 2015).
brain cancer (4 papers, 2012 to 2022). A primary or metastatic malignant neoplasm affecting the brain. "We will specifically address what molecular information we can use from appropriate cell systems and animal models of brain cancer in order to develop better MYCN-targeted treatments." (PMID 33585252, 2020). "Here, we will describe the prevalence of MYCN alterations in malignant brain cancer in children and adults." (PMID 33585252, 2020). "The generation of more clinically relevant models recapitulating such subgroups, including MYCN-driven brain cancers have helped improved our understanding how these biologically distinct tumors can be efficiently targeted." (PMID 33585252, 2020). "This would indicate that MYCN-driven brain cancers have a long way to go in this promising field." (PMID 33585252, 2020). "For example, while pediatric brain cancers are largely driven by epigenetic dysregulation and micro-environmental influences exert a greater effect on adult brain cancers, common molecular drivers between the two include MYCN, NOTCH, PI3K/AKT/MAPK/mTOR, WNT/−catenin, and SHH." (PMID 34055785, 2021).
cholangiocarcinoma (4 papers, 2020 to 2021). A carcinoma that arises from the intrahepatic biliary tree (intrahepatic cholangiocarcinoma) or from the junction, or adjacent to the junction, of the right and left hepatic ducts (hilar cholangiocarcinoma). "MYCN mRNA is a direct target of miR-520c-3p in cholangiocarcinoma, and transcription factor SP1-induced lncRNA HOXD-AS1 enhances MYCN expression through competitively binding to miR-520c-3p, which associates with lymph node invasion, advanced TNM stage and poor prognosis." (PMID 33614505, 2020).
diffuse midline glioma (4 papers, 2018 to 2025). A diffuse glioma that arises from the midline structures of the central nervous system. "Consequently, we compared the methylation profiles of K27M-mutated diffuse midline gliomas (including DIPG) to G34R-mutated tumors and well-characterized supratentorial tumors without mutation in histone H3 genes, i.e. MYCN and PDGFRA tumor subgroups." (PMID 30396367, 2018).
ependymal tumor (4 papers, 2019 to 2024). A group of neoplasms which arise from the ependymal lining of the cerebral ventricles and from the remnants of the central canal of the spinal cord. "Spinal ependymoma, MYCN-amplified also has a DNA methylation profile which is different from other ependymal tumors and CNS tumors with MYCN amplification." (PMID 38544524, 2024).
hepatoblastoma (4 papers, 2013 to 2025). Hepatoblastoma (HB) is a malignant hepatic tumor and is the most common pediatric liver cancer. "MYCN is a proto-oncogene encoding a basic helix–loop–helix transcription factor that is upregulated in hepatoblastoma and other pediatric liver tumors." (PMID 39851951, 2025).
lymph node metastases (4 papers, 2020 to 2025). "MYCN status, presence of lymph node metastases, use of irinotecan or topotecan, and radiotherapy were also univariate predictors of OS." (PMID 39998749, 2025). "We carried out logistic regression analyses of liver metastases, bone metastases, lymph node metastases, tumor size >10 cm, neuron-specific enolase (NSE) ≥370 ng/ml, and MYCN with the NB5 assay." (PMID 34055604, 2021).
serous ovarian carcinoma (4 papers, 2011 to 2025). "Our results associate deregulation of MYCN and downstream targets, including Let-7 and oncofetal genes, with serous ovarian cancer." (PMID 21533284, 2011). "Gain or over-expression of MYCN has not previously been associated with serous ovarian cancer." (PMID 21533284, 2011). "High-grade serous ovarian carcinoma with high expression of MYCN was sensitive to a BET inhibitor, suggesting that MCYN may be one of the drivers of the development of high-grade serous ovarian carcinoma." (PMID 39802403, 2025).
spinal cord ependymoma (4 papers, 2020 to 2025). An ependymoma that arises from the spinal cord. "This variant referred to as MYCN-amplified spinal cord ependymoma in the WHO 2021 classification is defined by the presence of a MYCN amplification and is considered as grade 3." (PMID 39199553, 2024). "Together with the current study, 27 cases of MYCN amplified spinal cord ependymomas have been reported, all with aggressive behavior, and with the majority showing Grade III morphology." (PMID 32641156, 2020). "In addition, they were conducted before the WHO 2021 classification, and for example, there is no specific data regarding the treatment of the recently described MYCN-amplified spinal cord ependymoma entity." (PMID 39199553, 2024). "Therefore, a combined total of 27 MYCN amplified spinal cord ependymoma cases have now been reported in the literature, warranting their consideration as a distinctive subtype of spinal cord ependymoma (SP-EPN-MYCN) with their unique molecular characteristics and aggressive clinical behavior." (PMID 32641156, 2020). "We report a novel group of clinically aggressive spinal cord ependymomas characterized by Grade III histology, MYCN amplification, an absence of NF2 alterations or other recurrent pathogenic mutations, and a unique methylation classifier profile." (PMID 32641156, 2020).
squamous cell carcinoma (4 papers, 2016 to 2023). A carcinoma arising from squamous epithelial cells. "Although we identified a significant impact of MYCN-expression levels on progression free survival in both the cohort investigated as a whole, and in the squamous cell carcinomas alone, this was not validated in the TCGA data." (PMID 26858029, 2016).
viral infection (4 papers, 2015 to 2023). "To explore the underlying mechanism of the virus-mediated antitumor effect against MYCN-amplified NB cells, we investigated the expression of apoptosis- and autophagy-related proteins on day 3 after virus infection using western blot analysis." (PMID 32637577, 2020). "These tumors can harbor amplification of the MYCN oncogene, altered pRB phosphorylation by PIN1 gene, or caused by viral infection." (PMID 25602518, 2015). "In contrast, non-MYCN-amplified NB cells showed apoptosis and autophagy after virus infection." (PMID 32637577, 2020).
basal cell carcinoma (3 papers, 2017 to 2023). A carcinoma involving the basal cells. "Copy number gains and amplification of MYCN have been identified in basal cell carcinomas and, as reported in other cancers, this is associated with aberrant cell growth." (PMID 28358317, 2017). "In basal cell carcinoma, increased sonic hedgehog (SHH) has been linked to increased MYCN." (PMID 28358317, 2017).